VRK1 (VRK serine/threonine kinase 1)
Diseases named in the same sentence as VRK1 in open-access papers (continued):
Sharing a sentence is not in itself a finding about the gene and the disease.
spinal muscular atrophy (18 papers, 2014 to 2025). A motor neuron disease that affect the muscles, and characterized by muscle weakness and atrophy resulting from progressive degeneration and irreversible loss of the anterior horn cells in the spinal cord (i.e., lower motor neurons) and the brain stem nuclei. "Electromyography and muscle biopsies in patients with pathogenic variants in VRK1 have been reported with features of neurogenic myopathy/atrophy or spinal muscular atrophy." (PMID 40048674, 2025). "Among the diseases associated with these VRK1 variants are spinal muscular atrophy (SMA), amyotrophic lateral sclerosis (ALS), distal hereditary motor neuropathies (dHMN), and Charcot-Marie-Tooth (CMT)." (PMID 38753965, 2024). "Very rare pathogenic VRK1 variants have been associated with distal neuropathies such as spinal muscular atrophy, amyotrophic lateral sclerosis, and hereditary spastic paraplegia, all of which have been linked to oxidative stress." (PMID 38732093, 2024). "These rare VRK1 variants are functionally involved in very severe motor neuron diseases, among which are spinal muscular atrophy, amyotrophic lateral sclerosis, and distal hereditary neurological diseases." (PMID 38732093, 2024). "Non‐SMN1‐related spinal muscular atrophies are caused by variants in a number of genes, including VRK1, encoding the vaccinia‐related kinase 1 (VRK1)." (PMID 31560180, 2019). "Very rare polymorphisms in the human VRK1 (vaccinia-related kinase 1) gene have been identified in complex neuromotor phenotypes associated to spinal muscular atrophy (SMA), pontocerebellar hypoplasia (PCH), microcephaly, amyotrophic lateral sclerosis (ALS) and distal motor neuron dysfunctions." (PMID 31527692, 2019). "Biallelic variants in VRK1 have been described in patients with heterogeneous phenotypes with childhood- or adult-onset progressive upper and lower motor neuron disease, including spinal muscular atrophy, amyotrophic lateral sclerosis, and hereditary spastic paraplegia." (PMID 40048674, 2025). "VRK1 pathogenic variants cuase defects in Cajal bodies, functionally altering neurons with long axons and leading to neurological diseases, such as amyotrophic laterla sclerosis, spinal muscular atrophy, distal hereditay motor neuropathies and Charcot-Marie-Tooth." (PMID 38753965, 2024). "Mutations in Vaccinia-related kinase 1 (VRK1) have emerged as a cause of severe neuronal phenotypes in human, including brain developmental defects and degeneration of spinal motor neurons, leading to Spinal Muscular Atrophy (SMA) or early onset Amyotrophic Lateral Sclerosis (ALS)." (PMID 30050127, 2018). "Rare recessive variants in the human VRK1 gene are associated with several motor neuron diseases (MND), such as amyotrophic lateral sclerosis, spinal muscular atrophy, or distal hereditary motor neuropathies (dHMN)." (PMID 38554151, 2024). "A rare germline mutation in VRK1 (R358X) results in lack of VRK1 protein production and manifests in pediatric patients as spinal muscular atrophy with pontocerebellar hypoplasia." (PMID 36040810, 2022).
lung carcinoma (16 papers, 2008 to 2024). "High VRK1 expression has been associated with poor prognosis in various cancers like head and neck, lung carcinomas or hepatocellular carcinomas." (PMID 33233777, 2020). "VRK1 is thus a new important regulator of cell proliferation, and high VRK1 protein levels have been associated with the proliferation phenotype in head and neck squamous cell carcinomas and lung cancer." (PMID 24079673, 2013). "It was already known that in a human lung carcinoma cell line, loss of VRK1 by siRNA resulted in reduced proliferation." (PMID 18286197, 2008). "High levels of VRK1 confer resistance to different treatments based on DNA damage; thus, VRK1 overexpression has been associated with poorer prognosis in some types of cancer, including multiple myeloma and lung cancer." (PMID 38753965, 2024). "High levels of wild-type VRK1 expression are associated with poorer prognosis in many types of cancer including multiple myeloma, lung cancer, head and neck squamous cell carcinoma, esophageal cancers, gastric cancer, liver, colon, breast, hepatocellular carcinomas, Wilms tumors and gliomas." (PMID 38753965, 2024). "Treatment of A549 human lung cancer cells with ursolic acid (0–50 μM) resulted in reduced cell viability and increased DNA damage associated with inhibition of vaccinia-related kinase 1 (VRK1) autophosphorylation and reduced phosphorylation of its downstream substrates, CREB and histone H3." (PMID 36364289, 2022). "Thus, we hypothesized that UA-induced VRK1 inhibition would render lung cancer cells more susceptible to DNA damage." (PMID 26412148, 2015). "It has been previously shown that VRK1 translation can be regulated, thereby promoting lung cancer cell proliferation." (PMID 37547297, 2023). "The expression level of VRK1 in lung cancer tissues was significantly higher than that in paraneoplastic tissues (P < 0.05)." (PMID 37547297, 2023). "Within 28 days, the tumor volume growth rate was the fastest in the shNC group, which was slowed down after knocking down VRK1, and the lung cancer tumor volume growth rate was the slowest in the shVRK1 + DOX group." (PMID 37547297, 2023). "And the tumor weight of lung cancer was significantly lower after knockdown of VRK1 compared with shNC, while the tumor weight of the shVRK1 + DOX group was significantly lower compared with the shVRK1 group." (PMID 37547297, 2023). "VRK1 relates to poor prognosis of glioma by participating in the PI3K/AKT pathway; studies have also shown that ginsenoside Rg3 affects DNA damage and causes VRK1 upregulation and P53BP1 foci formation, thereby inhibiting lung cancer cell viability." (PMID 35559251, 2022). "Altogether, our transcriptome analyses demonstrated that HNRNP A1 mRNA expression is enriched in lung tumors and that the level of HNRNP A1 or VRK1 is correlated with lung cancer patient survival." (PMID 34071140, 2021). "We further investigated the relationship between HNRNP A1 and VRK1 in lung cancer samples and lung cancer cell lines." (PMID 34071140, 2021).
lung carcinoma (continued). "To further support the role of HNRNP A1 in VRK1 3′UTR-mediated translation of lung cancer cells, we wanted to test the properties of the cell line with the cis-acting region deleted as we have done previously." (PMID 34071140, 2021). "We showed that the depletion of HNRNP A1 inhibits the VRK1-mediated phosphorylation of CREB in A549 lung cancer cell line." (PMID 34071140, 2021). "Altogether, our findings identified that VRK1, a key regulator of lung cancer cell proliferation, is a translation target of HNRNP A1." (PMID 34071140, 2021). "This enabled us to confirm the translational regulation of endogenous VRK1 3′UTR by HNRNP A1 and examine the VRK1-mediated role of HNRNP A1 in lung cancer cells." (PMID 34071140, 2021). "This suggests that VRK1 3′UTR is important for the enhancement of VRK1 protein levels and that HNRNP A1 regulates lung cancer cell progression via VRK1 3′UTR-mediated translational regulation." (PMID 34071140, 2021). "The expression levels of HNRNP A1 alone or in combination with VRK1 in patients with lung cancer are important because they provide not only a predictor for lung cancer prognosis but also a potential therapeutic target in lung cancer." (PMID 34071140, 2021). "Our analyses indicated that higher HNRNP A1 and VRK1 mRNA expression was correlated with the poor overall survival of patients with lung cancer." (PMID 34071140, 2021). "Herein, we report that VRK1 is post-transcriptionally upregulated in lung cancer cells, leading to the increased expression of CCND1." (PMID 34071140, 2021). "Recent work has focused on vaccinia-related kinase 1 (VRK1) as a possible drug target for lung cancer treatment." (PMID 26412148, 2015). "To this end, we employed CREB and histone H3, two representative VRK1 substrates, in lung cancer cells." (PMID 26412148, 2015). "By measuring 53BP1 foci formation, we found that UA inhibits the DNA damage defense activity of VRK1 and induces lung cancer cell death." (PMID 26412148, 2015). "It has also been proposed that in lung cancer and rhabdomyosarcoma, the VRK1 gene is a “druggable target gene” whose function in tumors is distinguishable from that in healthy tissue." (PMID 26375549, 2015). "UA weakens surveillance mechanisms by blocking 53BP1 foci formation induced by VRK1 in lung cancer cells, and possesses synergistic anti-cancer effects with DNA damaging drugs." (PMID 26412148, 2015). "We found that siRNA-mediated depletion of VRK1 caused G1 arrest in HCC cells, which is consistent with previous observations in H460 and H1299 lung cancer cells and MCF 10A mammary epithelial cells." (PMID 26375549, 2015). "In studies of the rewiring of the mitotic network, VRK1 was identified as a critical mitotic protein kinase in proliferation of lung cancer." (PMID 25310002, 2014). "It means that VRK1 is a potential druggable target in the lung cancer-specific mitotic network, because its gene expression is specific for the cancer cell cycle network and correlates with cell cycle markers." (PMID 25310002, 2014). "The level of VRK1 protein regulates the formation of 53BP1 DNA-repair foci induced by ionizing radiation in lung cancer cell lines." (PMID 24731990, 2014). "Five LUSC cell lines and BEAS-2B (human normal lung epithelial cells) were selected for the detection of VRK1 expression levels, and the results showed that VRK1 expression levels were significantly higher in lung cancer cell lines than in normal lung cell lines." (PMID 37547297, 2023). "HnRNPA1 could augment the proliferation activity of lung cancer cells by directly binding to the 3ʹUTR of vaccinia related kinase 1 (VRK1) mRNA, expediting its translation and then increasing cyclin D1 expression." (PMID 35879279, 2022).
lung carcinoma (continued). "Thus, our study unveils a novel role of HNRNP A1 in lung carcinogenesis via post-transcriptional regulation of VRK1 expression and suggests its potential as a therapeutic target for patients with lung cancer." (PMID 34071140, 2021). "Importantly, a correlation was found between HNRNP A1 or VRK1 expression and poor prognosis for patients with lung cancer." (PMID 34071140, 2021). "Importantly, only CRISPR/CAS9-mediated deletion of the cis-acting element on VRK1 3′UTR decreased VRK1 protein levels, resulting in a reduction of lung cancer cell proliferation." (PMID 34071140, 2021). "Furthermore, HNRNP A1 binding to the cis-acting region of the 3′UTR of VRK1 mRNA contributes to increased lung cancer cell proliferation." (PMID 34071140, 2021). "We report that HNRNP A1, a novel pro-tumorigenic RBP in lung cancer, contributes to lung cancer cell proliferation by promoting the expression of the oncogene VRK1 by binding to 3′UTR of VRK1 mRNA, leading to enhanced VRK1 mRNA translation in lung cancer cells." (PMID 34071140, 2021). "In short, our data demonstrated that HNRNP A1 is an important pro-tumorigenic factor in lung carcinogenesis and the therapeutic targeting of HNRNP A1/VRK1 may offer options for human lung cancer intervention." (PMID 34071140, 2021). "Furthermore, it is known that high VRK1 protein levels confer a stronger resistance to treatment in breast and lung cancer." (PMID 33233777, 2020). "In accordance with this, we observed that in lung cancer cells, the siRNA mediated loss of VRK1 also generates γ-H2A.X, suggesting that a lack of VRK1 induces DSBs by interfering with the repair system." (PMID 26412148, 2015). "Consistent with the decrease in phospho-CREB (p-CREB) levels, CCND1 mRNA levels also decreased in response to UA treatment in a concentration-dependent manner in lung cancer cells, suggesting that UA blocks the VRK1 downstream signaling pathway, as well as its enzymatic activity." (PMID 26412148, 2015). "Aberrant VRK1 expression has been reported in colon cancer and lung cancer tissues." (PMID 26375549, 2015). "On the other hand, VRK1 is a mitotic kinase that is expressed in normal cells like other mitotic kinases, but it has significant function in the growth of some tumors such as lung cancer and head and neck squamous cancer." (PMID 25310002, 2014). "In addition, the expression levels of VRK1 protein in three pairs of lung cancer and paraneoplastic tissues were examined by WB assay, and the results showed that the protein expression levels of VRK1 in lung cancer tissues were significantly higher than those in paraneoplastic tissues (P < 0.05)." (PMID 37547297, 2023). "To further see whether the effects of regulation by HNRNP A1 in lung cancer cells proliferation were obtained through VRK1 mRNA translation and more precisely in a 3′UTR-dependent manner, we generated a genome-edited A549 cell line lacking the cis-acting region of VRK1 3′UTR." (PMID 34071140, 2021). "Consequently, these critical roles for VRK1 suggest that it could be an excellent candidate for lung cancer therapy." (PMID 26412148, 2015). "To evaluate the role of VRK1 in LUSC, we first analyzed VRK1 expression in lung cancer tissues and paraneoplastic tissues using the GEPIA database (num (T) = 486; num (N) = 338)." (PMID 37547297, 2023). "VRK1 3′UTR was inserted between the two reporter genes, hRluc and hluc+ and the ratio of hRluc/hluc+ was measured in A549 and H1299 lung cancer cell lines as a representation of translation activity." (PMID 34071140, 2021). "Scatter plot analyses revealed a weak correlation between HNRNP A1 and VRK1 mRNA levels in lung cancer tissues; however, lung cancer cells had significantly higher HNRNP A1 and VRK1 protein expression than normal lung cells." (PMID 34071140, 2021). "In GSE43458 and 181 lung cancer cells, a weak positive correlation was found between HNRNP A1 and VRK1 mRNA expression." (PMID 34071140, 2021).
lung carcinoma (continued). "In this study, we investigated the regulation of VRK1 gene expression and assessed the role of HNRNP A1 in the proliferation of the lung cancer cell." (PMID 34071140, 2021). "This deletion resulted in low levels of VRK1 protein and phosphorylated CREB and, subsequently, suppressed lung cancer cell proliferation." (PMID 34071140, 2021). "Consistent with our TCGA findings, HNRNP A1 and VRK1 expression was significantly upregulated in lung cancer cells compared with normal cells and the expression of HNRNP A1 and VRK1 was positively correlated (R2 = 0.7403, p < 0.01)." (PMID 34071140, 2021). "To corroborate our TCGA findings, we next looked for the expression of HNRNP A1 and VRK1 in normal lung cell lines (lung fibroblast cell line (LF) and lung smooth muscle (LSM)) and lung cancer cell lines via immunoblotting." (PMID 34071140, 2021). "The translational efficiency of VRK1 mRNA is increased by its binding to the 3’-untranslated region of hnRNPA1, and thus potentiates the expression of CCND1 (cyclin D1) mediated by phosphorylation of CREB, which promotes lung cancer tumor cell proliferation." (PMID 38753965, 2024). "To understand the effect of HNRNP A1 in VRK1-mediated cell cycle progression of lung cancer cells, we performed FACS analysis in cells without the cis-acting region." (PMID 34071140, 2021). "The expression of HNRNP A1 and VRK1 at the transcripts level was measured using publicly available datasets of lung cancer tissues compared with non-tumor tissues." (PMID 34071140, 2021). "VRK1 has been focused on a suitable target for lung cancer treatment because VRK1 is related to cell cycle and DNA damage response in lung cancer tissue, not normal tissue." (PMID 25310002, 2014).